TNF (tumor necrosis factor)
Diseases named in the same sentence as TNF in open-access papers (continued):
Sharing a sentence is not in itself a finding about the gene and the disease.
dengue (continued). "In this study, the expression profile of several important inflammation mediators, including TNF-α, IL-1α, IL-1, IFN-γ and IL-10, was investigated in dengue patients at different time points." (PMID 27301555, 2016). "As detected by in situ hybridization and IHC, the dengue case showed many areas of co-expression in the hepatic tissue considering DENV RNA and IFN-γ or TNF-α." (PMID 28006034, 2016). "The number of cells producing of TNF-α and IFN-γ in dengue cases was 3- and 5-fold higher, respectively, after comparison with non-dengue cases." (PMID 28006034, 2016). "Patients with severe dengue have been reported to display elevated levels of TNFα and in several AG129 ADE models, TNFα blocking antibodies were found to delay the death of DENV2-infected mice." (PMID 27007501, 2016). "RANTES, also known as CCL5, is an early expressed chemokine induced by pattern recognition receptors, but can also be induced by TNF-α and IFN-γ at late stages of infection, that is the case of a terminal dengue situation." (PMID 28006034, 2016). "Along with TNF-α, IFN-γ was also found to be increased in terms of production by infiltrated mononuclear cells in peripheral tissues of the studied fatal dengue cases." (PMID 28006034, 2016). "However, contradictory data for the role ofTNF-α in severe dengue has also been observed in genetic studies, in which a TNF-α genepolymorphism (-308A allele) has been associated not only with severe disease, but alsowith protective effects against DHF (Fernández-Mestre etal." (PMID 27008374, 2016). "Many studies have demonstrated that levels of inflammation mediators such as TNF-α, IFN-γ, IP-10, IL-8 are elevated in dengue patients and higher levels in severe cases." (PMID 27301555, 2016). "In our previous study, several genes involved in the TLR6 pathway have been found to be significantly up-regulated during dengue virus infection in K562 cells on day 3 post-infection which include TLR6, IL-6, TNF-α and CD80." (PMID 26226614, 2015). "Among those that responded, DV2-infected wild-type mice secreted higher amount of TNF-α compared to that of the DV2-infected TLR6-/- mice, indicating that TLR6 activation contributed to the TNF-α expression during dengue virus infection." (PMID 26226614, 2015). "For example, high levels of circulating pro-inflammatory cytokines such as IL-1β or TNF-α in DENV-infected patients correlates with severe dengue fever, compared to patients suffering with mild dengue fever." (PMID 25521078, 2014). "Anti-enolase antibodies induced apoptosis in endothelial cells and production of inflammatory mediators by monocytes and macrophages, including TNF-α, IL-1β and IFN-γ, which are also increased in the plasma of dengue patients." (PMID 25171719, 2014). "We evaluated NO, NS1 serum levels (ELISA), TNF-α production by peripheral blood mononuclear cells (PBMCs), and TLR4 expression on CD14+ cells from 37 dengue patients and 20 healthy controls." (PMID 25580138, 2014). "Elevated serum levels of an ever increasing list of soluble mediators (such as TNFα, IL-6, C5a, VEGF, MMP-9 and others) have been measured in DHF/DSS patients and represent hallmarks of severe dengue." (PMID 24699622, 2014). "Several observations suggest a massive T-cell activation during DHF, producing cytokines (interferon γ, interleukin 2, TNF α) and infected cell lysis by CD4+ and CD8+ dengue specific lymphocytes are responsible for plasma leakage." (PMID 25242847, 2014). "High levels of cytokines, such as TNF alpha (TNFa), IFN gamma (IFNg), have been detected in patients with severe dengue." (PMID 23978258, 2013). "Levels of TNF-α, thrombomodulin and VWF were significantly increased in the two dengue groups than in healthy controls, but similar between patients with and without bleedings." (PMID 23890510, 2013).
dengue (continued). "Moreover, high serum levels of TNF-α, IL-1β, IL-6, CXCL-8/IL-8, and IL-10 correlated with severity of the disease in dengue patients, showing a preponderant role of NF-kB-dependent inflammatory response in dengue immunopathogenesis." (PMID 40934228, 2025). "As for dengue NS1, we also detected the production of TNF-α and IL-10 by mouse splenocytes." (PMID 36674524, 2023). "Since the levels of TNF-α, IL-6, and SOCS3 in the blood are higher in dengue-infected patients with hemorrhagic fever or shock (severe dengue) than those in patients with fever only, it suggests that overt inflammatory responses are detrimental to DENV-infected hosts." (PMID 36930690, 2023). "Although, there are some studies showing that IL-6, IL-10 and TNF-α are related to dengue, the roles of IL-37b in dengue fever have not been established." (PMID 37024713, 2023). "Our results demonstrate increased levels of TNF-α and MCP-1/CCL2 in patients that evolved with either mild dengue or warning signs and severe dengue syndromes, while higher levels of IFN-ɣ, RANTES/CCL5 and IL-1β were observed only in plasma from patients presenting warning signs and severe dengue." (PMID 36569864, 2022). "Therefore, increased IL-18 and IL-8, probable increased IL-6 and TNF-α together with decreased IFN-γ and RANTES in acute SDD patients resemble cytokine involvement in severe dengue progression." (PMID 34734091, 2021). "When stimulated with TLR9 agonist CpG, we have shown that activation markers CD69 and CD86 were not up-regulated and that no secretion of IL-10 and TNF-α was observed in B cells from dengue patients compared to healthy donors." (PMID 34293057, 2021). "The levels of CRP (p < 0.0001), SAP (p < 0.0001), ferritin (p < 0.0001), TNF-α (p < 0.0001) and IL-1β (p < 0.0001) were high in patients with Severe Dengue as compared to Dengue without warning signs." (PMID 33436908, 2021). "On the contrary and in contrast to findings in Dengue virus infection, our findings do not support a key role for TNF in AVHF pathogenesis." (PMID 33803310, 2021). "Thus, we examined the impact of AQCH drug substance treatment in the secondary dengue AG129 model on serum viremia as well as markers of small intestinal pathology, viz., viral load, vascular leakage, and TNF-α and IL-6 levels." (PMID 34912307, 2021). "Moreover, pinocembrin and pinostrobin were well known to downregulate pro-inflammatory cytokines (e.g., TNF-α, IFN-γ, IL-6) in monocyte/macrophage, thus alleviated the burden of dengue immunopathogenesis." (PMID 32932762, 2020). "At the time of plasma leakage, elevated levels of permeability-enhancing factors, tumor necrosis factor-α (TNF-α) and vascular endothelial growth factor-A (VEGFA) are found in severe dengue patients and contribute to three main pathological features: plasma leakage, hemorrhage and coagulopathy." (PMID 32545679, 2020). "CD19+CD24hiCD38hi and CD19+CD27− B cells from dengue patients were refractory to TLR stimulation in vitro, resulting in decreased B-cell-specific IL-10 and TNF-α cytokine production, which correlates to an increased expression of inhibitory FcγR in vivo in naïve B cells from DENV-infected patients." (PMID 31736948, 2019). "Some reports analyzing dengue-infected patients have not observed a significant difference between TNF-α levels from dengue fever and severe dengue." (PMID 31333657, 2019). "Among the host inflammatory biomarkers, GM-CSF, IFN-γ, IL-10, IL-15, IL-8, MCP-1, IL-6, MIP-1β, and TNF-α levels were significantly increased in dengue with and without warning signs, in severe dengue patients in comparison to healthy controls." (PMID 30626045, 2019). "Elevated levels of TNF-α and soluble TNF-α receptors have been reported in severe cases of dengue." (PMID 31333657, 2019). "An in vitro study has reported that acute dengue sera had significantly high TNF-α levels, and the endothelial activation was inhibited more than 70% with pre-treatment of monoclonal antibodies against TNF-α." (PMID 30300401, 2018).
dengue (continued). "Increased numbers of TNF-α-, IFN-γ-, IL-10- and TGF-β- expressing cells such as macrophages and lymphocytes were characterized in the tissues of dengue cases, when compared to controls." (PMID 28006034, 2016). "Moreover, higher level of TNF-α (P =0.004) on day 6–7 and higher levels of IL-1α (P = 0.012) and IFN-γ (P = 0.001) on day 8–10 of illness were observed in severe dengue patients than mild ones." (PMID 27301555, 2016). "Upon dengue virus infection, PBMC secretes both IL-6 and TNF-α." (PMID 26226614, 2015). "Among important innate immune parameters that could be affected by dengue NS1 levels, NO and TNF-α seem to be very important molecules." (PMID 25580138, 2014). "We speculate that in our cohort of dengue-infected patients, independently of CR3 expression on monocytes, monocytes remain as an important source of TNF, inducing an important systemic effect that would help the host to eradicate infection." (PMID 25061945, 2014). "We did not observe significant production of TNFα, IL-10, IL-4, IL-13, IL-17 by dengue NS3-specific T cells, suggesting a different source for these cytokines in the serum." (PMID 23209731, 2012). "Il-17 is the signature cytokine of the newly described T helper 17 (Th-17) cell population and has been proposed as the founding member of a new subclass of proinflammatory cytokines involved in dengue, eliciting cytokines such as Il-6, Il-8, MCP-1, GRO-α and TNF-α." (PMID 21167041, 2010). "Of note, TNF-α is one of the major NF-κB pathway effector molecules and others showed that in two independent mouse models of dengue infection, antibodies to TNF-α significantly decreased dengue disease severity and mortality in vivo." (PMID 18398488, 2008). "Infection also induced neutrophil infiltration in the small intestine, and increased expression of IL-6 and MMP-8 and blockade of TNF-α signaling protected the mice, as demonstrated in a previous severe dengue mouse model using C57/BL6 mice lacking both IFN-α/β and IFN-γ receptors." (PMID 38550855, 2024). "But unexpectedly, we could not detect IL-1β, IL-17A or TNF-α in dengue samples because of off-target." (PMID 37024713, 2023). "Based on the extensive literature on serum cytokines in dengue patients that implicates these soluble mediators in protection/severity, we chose to query TNF-α, IP-10, IL-6, and IL-10 from monocytes and granulocytes along with TNF-α, IP-10, IL-10, and IFN-γ from NK and NKT cell subsets." (PMID 34335578, 2021). "The results obtained by Kleber and colleagues showed that CQ suppressed TNF-α and IFN-γ production, and it was hypothesized that CQ might be used to treat patients suspected of having dengue disease, avoiding the more severe form of dengue hemorrhagic fever and/or shock." (PMID 31936284, 2020). "In dengue patients the nine plasma cytokine levels were significantly elevated when compared to healthy controls: GM-CSF, IFN-γ, IL-10, 1L-15, IL-8, MCP-1, IL-6, MIP1β, and TNFα (p = 0.008, 0.0001, 0.0001, 0.0003, 0.0001, 0.001, 0.0003, 0.001 and 0.006 respectively) levels." (PMID 30626045, 2019). "Furthermore, there was no significantly increased concentration of TNFα in the skin, providing additional evidence that tipDCs do not infiltrate into skin during severe dengue disease." (PMID 29079750, 2017). "Non-dengue tissues exhibited little or none expression of RANTES, VEGFR-2 and VCAM-1, however, TNF-α was detected in cells around the centrilobular vein." (PMID 37457689, 2023). "Four eligible biomarkers, CRP, TNF-α, IL-10, and IFN-γ, found no significant variation in marker levels when comparing severe and non-severe dengue." (PMID 34610027, 2021). "We found that whilst patients with severe dengue had lower total T cell numbers, the DV-NS3 specific T cells persisted and produced high levels of IFNγ but not TNFα, IL-3, IL-13, IL-2, IL-10 or IL-17." (PMID 23209731, 2012).
dengue (continued). "Many studies have investigated the cytokines patterns in serum samples in patients with DHF and these studies have shown that TNFα, IL-6, IL-10, IL-1β, IFN-γ, IL-4, IL-13, IL-7, GM-CSF, MIF, along with several other cytokines were elevated in patients with DHF when compared to dengue fever (DF)." (PMID 23209731, 2012). "Furthermore, a positive correlation between TNF-α and MDA, a product of polyunsaturated lipid degradation by ROS, has been reported in complicated but not uncomplicated cases of dengue." (PMID 39852665, 2025).
migraine (204 papers, 2008 to 2026). "Classically, TNFα and IL-6 have been associated in literature with migraine, as they are central mediators of both systemic and neurogenic inflammation." (PMID 41010614, 2025). "Pro-inflammatory cytokines such as IL-1β, IL-6, IL-8, and TNF-α are implicated in both migraines and GIDs, contributing to visceral pain and systemic inflammation." (PMID 39861467, 2025). "This analysis revealed significant downregulation of NOS2 (inducible nitric oxide synthase) along with key migraine‐associated inflammatory factors, including TNF‐α, IL‐6 and CGRP." (PMID 41194575, 2025). "Mechanistically, Mt2 regulates cerebrovascular compliance via modulating the release of migraine‐associated mediators (CGRP, IL‐6, TNF‐α), thereby establishing an interface between vascular tone dysregulation and migraine‐like pain thresholds." (PMID 41194575, 2025). "A systematic literature survey method with a mixture of keywords was utilized to grasp the different elements that represent the association between TNF-α and migraine." (PMID 38213956, 2024). "A second meta-analysis of five studies on Asian population found a link between TNF-α and 308G/A polymorphisms with the incidence of migraine." (PMID 38699683, 2024). "Several cytokines, including tumor necrosis factor alpha, interleukin 1, and adiponectin, have been implicated in the pathogenesis of migraine." (PMID 37721571, 2024). "Continuous pieces of evidence of an association between the TNF gene and migraine have been collected, with the most noteworthy finding coming from Franceschini and colleagues." (PMID 38213956, 2024). "In this review, we aimed to provide a culminating and comprehending glimpse into the TNF-α in association with the migraine." (PMID 38213956, 2024). "In a recent meta-analysis, IL-6, IL-8, IL-1β, and tumor necrosis factor α were the proinflammatory cytokines implicated in migraine patients." (PMID 38369488, 2024). "First, proinflammatory cytokines, such as interleukin (IL)-1b, IL-6, IL-8, and tumor necrosis factor-α, have been implicated in migraine pain and are increased during migraine attack, which play a critical role in the pathogenesis of IBD30." (PMID 38212517, 2024). "Elevated serum levels of TNF-α have also been linked with endothelial dysfunction, which is reportedly present in migraine patients." (PMID 36982428, 2023). "Other cytokines, including IL-10 and tumor necrosis factor alpha (TNF-α), have shown associations with migraine." (PMID 37755358, 2023). "This currently updated meta-analysis utilizes the different genetic models to observe the effect of the rs1800629 variant of TNF-α on migraine susceptibility." (PMID 37085790, 2023). "Apart from such conflicting and diverse results, all meta-analyses confirmed that the risk of migraine was greater in the Asian population than in the Caucasian population concerning the risk allele of TNF alpha (rs1800629)." (PMID 37085790, 2023). "Genetic factors have impacted incredibly on the susceptibility of migraine and one such example is the TNF-α 308G > A." (PMID 37085790, 2023). "A genetic study focusing on the TNF-alpha gene polymorphisms (rs1800629 and rs1799724) among Jordanian migraineurs showed its significant associations with migraine occurrence." (PMID 36835524, 2023). "The connection between TNF-α and migraine is particularly noteworthy, given the repeated association of elevated levels of this cytokine with endothelial dysfunction." (PMID 37755358, 2023). "Genetic analysis of cytokines suggests that TNF-α and other cytokines are involved not only in the risk of migraine but also in the pathophysiology during attacks." (PMID 37176049, 2023). "Pro-inflammatory cytokines such as IL-1, IL-6, IL-8, and TNF-α, have also been linked to migraine pain and are elevated during episodes." (PMID 36168375, 2022). "In particular, we demonstrated the presence of the pro-inflammatory cytokines TNFα and IL-6, known to be associated with migraine pathology." (PMID 35614095, 2022).